CD68 (CD68 molecule)
Diseases named in the same sentence as CD68 in open-access papers (continued):
Sharing a sentence is not in itself a finding about the gene and the disease.
interstitial nephritis (2 papers, 2015 to 2025). Inflammation of the renal tubules and supporting tissues of the kidney. "The fact that CD68-positive cellular infiltration was prominent in the interstitium suggested that although there were no typical giant cells, a foreign body reaction to the suspect drug may have occurred, which may have activated T cells and caused interstitial nephritis." (PMID 40569518, 2025). "A significant positive correlation has been reported in the PAN model between the severity of interstitial nephritis, as determined by increased CD68 positive macrophages, MCP-1 and IL-1β, and the degree of proteinuria." (PMID 26014479, 2015).
Langerhans cell sarcoma (2 papers, 2019). A neoplastic proliferation of Langerhans cells with overtly malignant cytologic features. "In human Langerhans cell sarcoma (LCS), TIM-1 could be found in cancer cells, CK-18-positive epithelial cells and CD68-positive macrophages." (PMID 31138322, 2019).
leiomyoma (2 papers, 2021 to 2022). A well-circumscribed benign smooth muscle neoplasm characterized by the presence of spindle cells with cigar-shaped nuclei, interlacing fascicles, and a whorled pattern. "They found that there were far more CD68 macrophages in leiomyomas and their surrounding tissues than in the distant myometrium." (PMID 36703761, 2022). "On the other hand, our group noticed that cellular leiomyomas, in addition to higher levels of CD68 positive macrophages, also have an increased number of leukocytes and mast cells that are other types of inflammatory cells." (PMID 33922329, 2021). "More precisely, by CD68 staining, our group found that macrophages predominantly localize inside leiomyoma and in the myometrium tissue next to leiomyoma." (PMID 33922329, 2021). "Since these results were obtained by studying different histotypes of leiomyomas, we could add that the reported macrophage localization is valid for both cellular and usual leiomyomas with the cellular leiomyoma showing higher levels of CD68-positive macrophages compared with usual leiomyoma." (PMID 33922329, 2021).
lymphadenopathies (2 papers, 2021 to 2025). "The transient thoracic lymphadenopathy and predominance of CD68-positive macrophages in pericardial fluid further support a macrophage-driven inflammatory response, even though the absence of pleural fluid sampling limits full characterization." (PMID 40861729, 2025).
lymphopenia (2 papers, 2021 to 2023). Reduction in the number of lymphocytes. "Taken together, these data demonstrate that CD117-sap + mATG enabled high-level engraftment of CD68-ECO-ET3-LV modified donor LT-HSCs in the absence of prolonged lymphopenia in a majority of HSCT recipients." (PMID 34141826, 2021).
malignant meningioma (2 papers, 2023 to 2024). "Recent studies have indicated that CD47 expression in malignant meningiomas was increased while the number of T cells was decreased, and the number of macrophages expressing CD68 was increased." (PMID 38404571, 2024). "We found that the expression of CD47 was increased in malignant meningioma along with a decreased number of T cells and an increase in CD68+ macrophages." (PMID 37171006, 2023). "Meanwhile, we found that CD68+ macrophages showed an increased expression in malignant meningioma, which indicated blocking CD47 maybe a potential therapeutic target for malignant meningioma." (PMID 37171006, 2023).
measles (2 papers, 2018 to 2019). A highly contagious viral infection caused by the measles virus. "Additionally, we observed increased sinus histiocytosis (Iba1-, CD68-, and lysozyme-expressing cells) in these dolphins, recapitulating features observed in acute/subacute measles and distemper." (PMID 30936878, 2019).
mesenchymal tumor (2 papers, 2014 to 2022). "Subsequent microscopic examination and immunohistochemical analysis revealed a phosphaturic mesenchymal tumor mixed connective tissue variant (PMTMCT) showing a positive expression of somatostatin receptor 2A (SSTR2A), CD68, and Periostin." (PMID 25221676, 2014).
muscular dystrophy (2 papers, 2018 to 2022). Muscular dystrophy (MD) refers to a group of more than 30 genetic diseases characterized by progressive weakness and degeneration of the skeletal muscles that control movement. "CD68 quantity is reportedly increased in several conditions such as muscle damage in untrained exercise, muscular dystrophy, Placenta of diabetic rats, in the islets of Langerhans in diabetic subjects." (PMID 36685197, 2022). "In comparison, only a small minority of tissue-infiltrating CD68+ cells in DM and in muscular dystrophy tissues were SLC6A12 positive, and the more sparse inflammatory cells observed in IMNM tissues were SLC6A12 negative." (PMID 30364257, 2018).
myelofibrosis (2 papers, 2021 to 2025). A partial or complete replacement of the bone marrow stroma by fibrous tissue. "CD68 alone showed excellent diagnostic accuracy for the prediction of secondary myelofibrosis (AUC = 0.851, 95% CI 0.78–0.92; specificity = 100%)." (PMID 41239536, 2025). "Regarding fibrotic progression, CD68 alone demonstrated excellent diagnostic accuracy for secondary myelofibrosis prediction, with an AUC of 0.851 (p < 0.001), achieving a specificity of 100% at a cutoff of less than 27.5." (PMID 41239536, 2025). "A CD68/CD163 ratio > 1.63 was significantly associated with shorter TFFS and secondary myelofibrosis PFS." (PMID 41239536, 2025). "ROC curve analyses demonstrated that the CD68/CD163 ratio provided the best diagnostic accuracy for both thrombosis and secondary myelofibrosis, outperforming individual markers." (PMID 41239536, 2025). "Prospective clinical cohorts will need to determine a correlative or predictive value of CD163 or CD68 as a parameter accompanying or predicting myelofibrosis." (PMID 33104881, 2021). "Using a cut-off of 1.63, the CD68/CD163 ratio yielded a sensitivity of 66.7% and specificity of 63.3% for thrombosis prediction (AUC = 0.677), and for secondary myelofibrosis, a cut-off of 1.55 gave a sensitivity of 80.9% and specificity of 75% (AUC = 0.779)." (PMID 41239536, 2025). "A CD68/CD163 ratio > 1.63 correlated with shorter thrombosis-free survival (41.4 vs. 68.2 months; p = 0.001; hazard ratio [HR] 2.45, 95% confidence interval [CI] 1.45–4.14) and secondary myelofibrosis progression-free survival (48.3 vs. 79.0 months; p = 0.001; HR 2.67, 95% CI 1.55–4.60)." (PMID 41239536, 2025).
myeloid leukemia (2 papers, 2013 to 2026). A clonal proliferation of myeloid cells and their precursors in the bone marrow, peripheral blood, and spleen. "Occasionally, myeloid leukemia can firstly present in skin, in which CD68 and lysozyme positivity could be observed and sometimes difficult to be distinguished from LCS." (PMID 23388086, 2013).
myocardial ischemia (2 papers, 2015 to 2024). A disorder of cardiac function caused by insufficient blood flow to the muscle tissue of the heart. "Aberrant deposition of collagen was associated with a marked increase in CD68-positive macrophage infiltration in cardiac tissue in mice subjected to myocardial ischemia/reperfusion (I/R) for 14 days compared to sham controls." (PMID 38892398, 2024).
nasal polyps (2 papers, 2006 to 2010). "CD68 RCAS1 positive cells were observed to migrate from the stroma of the nasal polyps through the epithelium (single cells seen within the epithelium) to the mucus." (PMID 20214821, 2010). "We then analyzed metallothionein, RCAS1, CD25, CD4, and CD68 in a sampling of 50 nasal polyps using the immunohistochemistry method." (PMID 20214821, 2010). "In the edematic area of the nasal polyp stroma, the number of inflammatory cells was high, and the number of CD68 positive cells increased to 8-11 in a hpf." (PMID 20214821, 2010). "The inflammatory infiltrate of nasal polyps consists of eosinophils, lymphocytes, mast cells, macrophage-like CD68+ cells." (PMID 16551346, 2006). "No other examined antigens (such as CD25, CD4, or CD68) were identified in the neutrophilic nasal polyps." (PMID 20214821, 2010).
neuroendocrine tumors (2 papers, 2016 to 2025). "Complement C5 is a chemoattactant for macrophages, and infiltration of neuroendocrine tumors by CD68+ macrophages has previously been reported to correlate with metastasis both in RT2 mice and in humans with pancreatic neuroendocrine tumors." (PMID 27105526, 2016). "Infiltration of lymphocytes (CD3+ or CD8+) and macrophages (CD68+ or CD163+) and expression of PD‐1/PD‐L1 were more pronounced in poorly differentiated neuroendocrine carcinoma compared to well‐differentiated neuroendocrine tumors, while CD68 and PD‐L1 correlated with advanced disease stage." (PMID 40145271, 2025).
osteoporosis (2 papers, 2020 to 2025). A condition of reduced bone mass, with decreased cortical thickness and a decrease in the number and size of the trabeculae of cancellous bone (but normal chemical composition), resulting in increased fracture incidence. "Here, we have observed RhoA activation in some of CD68+ cells accumulating at the pathological sites, suggesting a potential role for RhoA in activating osteoclasts, mediating osteoporosis of the bone tissue and promoting inflammation in dKO mice." (PMID 33361519, 2020).
periampullary adenocarcinoma (2 papers, 2016 to 2017). An adenocarcinoma that arises from the periampullary region. "Immune cell-specific expression of CD56, CD3, CD68 and CD1a was analysed by immunohistochemistry on tissue microarrays with tumours from 175 consecutive cases of periampullary adenocarcinoma, 110 of pancreatobiliary type (PB-type) and 65 of intestinal type (I-type) morphology." (PMID 27275582, 2016). "This study is, to our best knowledge, the first to investigate the prognostic role of tumour-infiltrating CD1a+, CD68+ and CD163+ and MARCO+ immune cells in periampullary adenocarcinoma, with particular reference to morphological type." (PMID 28673320, 2017).
peritonitis (2 papers, 2020 to 2025). Inflammation of the peritoneum (tissue that lines the abdominal wall and covers most of the organs in the abdomen). "CD68‐positive macrophages were significantly greater in peritonitis and EPS cases, with the highest increase observed in patients with peritonitis." (PMID 40977502, 2025). "This is one of the reasons why the number of CD68‐positive macrophages in the peritoneal tissues of the EPS cases was lower than that in the peritonitis cases, despite the high peritoneal thickness." (PMID 40977502, 2025). "Expression of CD68, a marker of macrophages, was upregulated in peritoneal tissues of WT and even more dramatically in Thbs4−/− mice with LPS-induced peritonitis." (PMID 31974349, 2020). "We compared the peritoneal thickness and expression of TG2, α‐SMA, and CD68 in the control group, patients treated with low‐GDP pH‐neutral solution, patients treated with conventional acidic solution, patients with peritonitis, and those with EPS." (PMID 40977502, 2025).
pituitary adenoma (2 papers, 2022 to 2025). "have determined the expression of CD68 (a pan-macrophage marker) in macrophages in pituitary adenoma tissue; however, the expression of CD68 was not studied in M2 macrophages." (PMID 35898456, 2022).
placental abruption (2 papers, 2021 to 2023). Vaginal bleeding preceding the 20th week of gestation. "In our population a higher number of placental macrophages was associated with placental abruption and a trend towards higher CD68+ cells in preterm placentas was shown, regardless of diagnosis of rheumatic diseases." (PMID 33313931, 2021). "Patients with histological evidence of placental abruption had a higher number of placental CD68+ cells, regardless of diagnosis." (PMID 33313931, 2021).
Pleural effusion (2 papers, 2018 to 2022). The presence of an excessive amount of fluid in the pleural cavity. "First, we demonstrate that DC-SIGN expression is present both in CD68+ macrophages found in tuberculous pulmonary lesions of non-human primates, and in the CD14+ cell population isolated from pleural effusions obtained from TB patients (TB-PE)." (PMID 29946317, 2018).
polymyositis (2 papers, 2023 to 2025). A rare idiopathic inflammatory myopathy characterized by symmetric proximal muscle weakness and elevated muscle enzymes. "A notable increase in CD68-positive monocyte-macrophages was observed in the myocardium of polymyositis patient, whereas CD68-positive cells are sparse in the myocardium of the patients with SLE." (PMID 41143174, 2025).
polyp (2 papers, 2013 to 2023). A usually exophytic mass attached to the underlying tissue by a broad base or a thin stalk. "Both the polyp and the colonic biopsies showed evidence of pTDP‐43 aggregation within the lamina propria (the mucosal connective tissue deep to the surface enterocytes) with examples of pTDP‐43 aggregates in CD68‐positive (i.e. activated) macrophages and in non‐CD68‐positive dendritic cells." (PMID 36226890, 2023). "Comparison with the mature CRSwNP further demonstrated that CD68 and MMR-positive cells were also significantly more pronounced in the polyp part of middle turbinate CRSwNP group than in the mature CRSwNP group (p= 0.006 and p=0.006, respectively)." (PMID 24340021, 2013).
prion disease (2 papers, 2016 to 2020). A transmissible disease that is caused by a protein that is able to induce abnormal folding of normal cellular proteins, leading to characteristic spongiform brain changes, which are associated with neuronal loss without an inflammatory response. "In order to evaluate the activation state of microglia at onset and end-stage prion disease in wild-type and Neil3 Ko mice we compared expression levels of microglial markers Cd68, Cd86 and inflammation markers TNFα and Il1ß at both time-points." (PMID 27886261, 2016). "However, to the best of our knowledge, the ability of CD68+ macrophages to transmit prion disease has not previously been demonstrated." (PMID 33195984, 2020).
psoriatic arthritis (2 papers, 2024). Joint inflammation associated with psoriasis. "Investigating CD68+ positive cells in the synovial tissue is crucial for understanding the pathogenesis of psoriatic arthritis (PsA) and developing targeted treatment strategies." (PMID 39629578, 2024).
pterygium (2 papers, 2011 to 2025). A wedge-shaped fibrovascular lesion arising from the bulbar conjunctiva and extending to the cornea. "Although T cells are the most frequently encountered type of inflammatory cell, CD68-positive macrophages are the next most commonly encountered in pterygium and they are distributed in both the epithelial and stromal layers, suggesting that they are related to disease pathogenesis." (PMID 22219642, 2011). "We observed a significant increase in the pterygium, with CD3-positive T lymphocytes showing a 1148 ± 175.4-fold increase (p < 0.001) and CD68-positive macrophages showing a 587.0 ± 53.99-fold increase (p < 0.0001) compared to the healthy conjunctiva." (PMID 40806545, 2025).
pulmonary hypertension (2 papers, 2019 to 2021). Increased pressure within the pulmonary circulation due to lung or heart disorder. "In a rat model of severe pulmonary hypertension, macrophages accumulated around pulmonary arterioles, and depleting CD68+ macrophages prevented the development of pulmonary hypertension." (PMID 31815093, 2019). "Similarly, intravenous injection of HIMF in mice increased CD68-positive inflammatory cells in the lung and caused VEGFR2 downregulation, showing that HIMF facilitates the pulmonary inflammation and angiogenesis that is often seen in pulmonary hypertension using VEGF." (PMID 33800244, 2021).
pulpitis (2 papers, 2012 to 2024). Inflammation of the dental pulp. "The changes in the recruitment of macrophages and antigen-presenting cells in the mild pulpitis model were evaluated by immunohistochemical analyses using CD68 and MHC class II antibodies, respectively." (PMID 23285075, 2012). "In the dog model of experimental pulpitis, luteolin treatment suppressed the expression of pPKR-, MPO-, and CD68-positive cells in pulp tissues, whereas guaiacol-parachlorophenol treatment caused coagulative necrosis and disruption." (PMID 38304347, 2024).
sacroiliitis (2 papers, 2018 to 2024). "Compared to SIJ controls, the subchondral microvessel density, number of CD68+ multinuclear osteoclasts, and the levels of VEGF, caspase-3, MMP-3, and TNF-α expressed at the interface of the bone and cartilage were significantly higher in patients with sacroiliitis." (PMID 29884210, 2018).
scrapie (2 papers, 2011 to 2020). A fatal disease of the nervous system in sheep and goats, characterized by pruritus, debility, and locomotor incoordination. "This study reports that experimental IC inoculation of CD68+ macrophages from scrapie-infected sheep into susceptible VRQ/ARQ and ARQ/ARQ sheep resulted in transmission to four out of eight animals (50 %)." (PMID 33195984, 2020). "At the completion of the study, we found that VRQ/ARQ and ARQ/ARQ sheep inoculated with CD11c+ B1 lymphocytes and CD68+ macrophages developed scrapie with detectable levels of PrPSc in the CNS and lymphoreticular system (LRS), while those inoculated with platelet-rich plasma did not develop disease." (PMID 33195984, 2020). "Additionally, the molecular profile of PrPSc from brainstem homogenates was analysed by Western blot to compare the migration patterns of sheep inoculated with CD11c+ B1 lymphocytes versus those inoculated with CD68+ macrophages that were positive for the scrapie agent." (PMID 33195984, 2020).
scrub typhus (2 papers, 2013 to 2015). Scrub typhus is a rare dust mite-borne infectious disease caused by the Orientia tsutsugamushi bacterium and characterized clinically by an eruptive fever which is potentially serious. "Cellular phenotyping of infected cells after euthanasia and completion of a natural disease course of scrub typhus revealed HLA-DR+ APCs and CD68+ (KP1) macrophages as the predominant cell phenotypes associated with intracellular O. tsutsugamushi." (PMID 25601925, 2015). "Recently, a paper reported that O. tsutsugamushi mainly infects “inflammatory” CD14/LSP-1/CD68 positive monocytes and CD1a/DCSIGN/S100/FXIIIa and CD163 positive dendritic cells in stained eschar skin biopsies from scrub typhus patients." (PMID 23301113, 2013).
serous carcinoma (2 papers, 2022 to 2024). "Serous carcinoma was the most immunogenic tumour, with CD3, CD20 and CD68 all demonstrating major associations with this subtype." (PMID 38674108, 2024). "Furthermore, CD68 intratumoral average was highest in serous carcinoma (p < 0.001)." (PMID 38674108, 2024).
Shock (2 papers, 2019 to 2021). The state in which profound and widespread reduction of effective tissue perfusion leads first to reversible, and then if prolonged, to irreversible cellular injury. "Patients who die during septic shock show strong, localized up-regulation of the microglial M1 polarization marker CD68 in the hippocampus." (PMID 34711216, 2021). "Based on the results of a pilot study in 8 patients, we assessed the number of MHC-II and CD-68 positive cells by immunohistochemistry and compared the number of microglia in specific brain regions of 16 well-characterized patients with septic shock and 15 controls." (PMID 31384283, 2019).
small cell lung carcinoma (2 papers, 2020 to 2021). Small cell lung cancer (SCLC) is a highly aggressive malignant neoplasm, accounting for 10-15% of lung cancer cases, characterized byrapid growth, and early metastasis. "For instance, anti-CD68 antibody KP-1 stains both macrophages and neutrophils in human non–small cell lung cancer tissue, while anti-CD68 antibody PG-M1 does not." (PMID 32752088, 2020). "In the small cell lung cancer tissue itself, 30% of dendritic cells, 15% of CD45 positive cells, no CD11b positive cells, and no CD68 positive cells were found." (PMID 33921688, 2021).